KRAS (KRas proto-oncogene, GTPase)
Diseases named in the same sentence as KRAS in open-access papers (continued):
Sharing a sentence is not in itself a finding about the gene and the disease.
lung adenocarcinoma (continued). "KRAS-mutant lung adenocarcinoma (LUAD), due to its evolution of more complex antioxidant metabolic mechanisms, exhibits poorer sensitivity to conventional platinum-based drugs compared to other types of LUAD." (PMID 41422226, 2025). "Our histological assessment identified EGFR and KRAS as predominant driver genes, consistent with a report showing at least eight pathological subtypes in lung adenocarcinoma." (PMID 40502411, 2025). "In comparison to PD-L1 inhibitor monotherapy, chemo-immunotherapy of PD-L1 blockade with paclitaxel significantly suppressed tumor growth in a mouse model of KRAS G12D-mutant lung adenocarcinoma (Top)." (PMID 39806421, 2025). "Deleterious LKB1 inactivation in KRAS-driven lung adenocarcinomas (LUACs) has been studied thoroughly; however, LKB1 inactivation is not limited in adenocarcinomatous histology, nor in KRAS mutational status." (PMID 38791897, 2024). "In KRAS-mutant lung adenocarcinoma, the inhibition of SLC7A11 reduces tumorigenesis, demonstrating its role in ferroptosis evasion under oxidative stress." (PMID 38539554, 2024). "Menin expression is downregulated in lung adenocarcinoma, at least partially through KRAS, a major driver of lung tumorigenesis, and the microRNA miR-802." (PMID 39336822, 2024). "These combinations showed synergistic antitumoral effects in all five KRAS-G12C mutant cancer models in 2D in vitro experiments and the findings were recapitulated in lung adenocarcinoma 3D models in vitro and in xenografts in vivo." (PMID 38278976, 2024). "While we utilized spleen cells pooled from WT C57BL/6J mice for the immune cell panel, we analyzed a pooled single-cell suspension of KRAS-driven lung adenocarcinoma for the TME panel." (PMID 38605953, 2024). "In this manuscript, we use lung adenocarcinoma cell line NCI-H23, derived from a Black male and carrying mutated KRAS, to study the effect of PCAIs on RAS pathway enzymes and signaling." (PMID 39436906, 2024). "Most notably, lung adenocarcinoma (LUAD) harbors those driver mutations and rearrangements that can be therapeutically addressed, such as EGFR, BRAF, ALK, ROS1, RET, NTRK, and also KRAS." (PMID 38846975, 2024). "Treating lung adenocarcinoma cells and tumor xenografts with MI-3 inhibits the growth of KRAS-mutant cell lines and tumors with minimal effect on the growth of wild-type KRAS lines and tumors." (PMID 39336822, 2024). "EGFR and KRAS are two of the most important driver genes in lung adenocarcinoma, accounting for a large proportion of cases." (PMID 39639005, 2024). "A recent study showed that ERK hyperactivation is toxic to lung adenocarcinoma driven by RTK and KRAS mutations." (PMID 39436655, 2024). "An analysis was conducted on a patient diagnosed with KRAS-G12C–mutant lung adenocarcinoma who exhibited resistance to AMG510 therapy after 13 weeks of treatment." (PMID 39661665, 2024). "Serine Threonine Kinase 11 (STK11) loss of function (LoF) correlates with anti-PD-1 therapy resistance in patients with KRAS-driven lung adenocarcinoma (LUAD)." (PMID 37968341, 2024). "A previous study has shown that in lung adenocarcinomas, p-ERK signaling can trigger PD-L1 expression in the presence of a KRAS mutation." (PMID 39201772, 2024). "KRAS mutations are the most common clonal oncogenic driver in NSCLC and are present in 35% of lung adenocarcinomas." (PMID 39037971, 2024). "The identification of novel therapeutic strategies to overcome resistance to the MEK inhibitor trametinib in mutant KRAS lung adenocarcinoma (LUAD) is a challenge." (PMID 38643157, 2024). "A short time later KRAS, a gene showing homologue features was detected in lung adenocarcinoma, located on the short arm of chromosome 12 at position 12p11.1-12p12.1." (PMID 38953007, 2024). "FAK inhibition in genetically engineered KRAS-driven mouse cancer models led to the regression of lung adenocarcinomas." (PMID 39271958, 2024).
lung adenocarcinoma (continued). "Combinations of clinically approved farnesyl-transferase inhibitors and KRAS G12C inhibitors are tested on human lung, colorectal and pancreatic adenocarcinoma cells in vitro in 2D, 3D and subcutaneous xenograft models of lung adenocarcinoma." (PMID 38278976, 2024). "A recent report indicated that an ongoing phase 1 study aims to identify the recommended expansion dose and assess the preliminary efficacy of MLN0128 and CB-839 in treating lung squamous cell carcinoma and KRAS-mutant lung adenocarcinoma." (PMID 39050886, 2024). "In lung adenocarcinoma tissues, the number of phospho-ADAM17-positive cells was significantly increased in KRAS-mutated tumors than in the tumors with wild-type KRAS." (PMID 38398101, 2024). "Combined genetic or pharmacological inhibition of ERK5 and CDK5 triggered ROS-induced DNA damage and apoptosis in cancer cells and mouse models of KRAS-driven lung adenocarcinoma, recapitulating FAK pharmacological inhibition." (PMID 39271958, 2024). "Previously, a general dependency of KRAS-mutated NSCLC on XPO1 was reported, and Selinexor monotherapy reduced tumor growth in multiple patient-derived lung adenocarcinoma xenografts." (PMID 38756650, 2024). "The initial screen for the expression of PD-L1 in different lung adenocarcinoma cell lines with wildtype KRAS (H1975, H1650 and H1299) and cell lines harboring KRAS mutations (A549, H460 and A427) showed the H460 and H1975 had the highest PD-L1 expression." (PMID 39201772, 2024). "Menin expression is inversely correlated with RAS expression in lung adenocarcinomas, and KRAS increases DNA methylation at the MEN1 promoter by upregulating DNMT1/3B and increasing DNMT1 recruitment to the menin promoter." (PMID 39336822, 2024). "The Hsp 90 inhibitor 17-DMAG can block IKK function and have better efficacy against KRASG12D-mutant lung adenocarcinoma, opening up a new way to prevent/treat KRAS-mutant LUAD." (PMID 38734764, 2024). "A major breakthrough was achieved with the recent development of mutant-specific KRASG12C inhibitors, which covalently bind to the novel cysteine residue present in nearly half of all patients with KRAS-mutant lung adenocarcinoma." (PMID 38635884, 2024). "We further explored the association between HOXC10 expression and the survival outcomes of patients in KRAS-mutant lung adenocarcinoma (LUAD) subgroups using TCGA datasets." (PMID 39191757, 2024). "Our observations on FTi sensitivity led us to combine tipifarnib, a clinically approved potent farnesyl-transferase inhibitor with sotorasib, a novel KRAS-G12C inhibitor in lung adenocarcinoma cell lines." (PMID 38278976, 2024). "It was of interest to screen the expression of PD-L1 in different lung adenocarcinoma cell lines with wildtype KRAS (H1975, H1650 and H1299) and cell lines harboring KRAS mutations (A549, H460 and A427)." (PMID 39201772, 2024). "Among KRAS mutations, the most common subtype is G12C, which accounts for 45% of all KRAS mutations in NSCLC and is detected in 13% of cases of lung adenocarcinoma." (PMID 39456995, 2024). "The experimental results showed that the NSD2 depletion combined with the MEK1/2 inhibition treatment regimen can significantly inhibit KRAS-mutant lung adenocarcinoma tumors." (PMID 38275900, 2024).
lung adenocarcinoma (continued). "Studies have shown that Chr-A has the potential to kill various tumors including lymphatic leukemia, melanoma and KRAS-mutant lung adenocarcinoma." (PMID 39330272, 2024). "The findings revealed that CD44 expression is up-regulated in KRAS-induced lung adenocarcinomas and that CD44 mediates KRAS-dependent MAPK activation and cell proliferation." (PMID 38672650, 2024). "Highly prevalent mutations in genes such as EGFR, KRAS, and ALK contribute substantially to lung adenocarcinoma and are pivotal for recommending targeted therapies." (PMID 39323996, 2024). "Activating mutations in the KRAS gene are a hallmark of cancer and the KRASG12C protein mutation is one of the most common activating alterations in lung adenocarcinoma." (PMID 38225225, 2024). "For example, among the top three exclusively mutated gene pairs are BRAF and NRAS in skin cutaneous melanoma (p = 1.1 × 10–44), KIT and PDGFRA in gastrointestinal stromal tumour (p = 3.3 × 10–37), and EGFR and KRAS in lung adenocarcinoma (p = 6.6 × 10–29)." (PMID 37550388, 2023). "KRAS expression is involved in the regulation of multiple oncogenes and tumorigenesis, especially in the prognosis and immune infiltration of lung adenocarcinoma." (PMID 38206735, 2023). "In subsequent versions of the NCCN guidelines, the panel of molecular tests was expanded to include BRAF, ROS-1, RET, ERBB2 (HER2), KRAS, and MET mutations as routine for patients with lung adenocarcinoma." (PMID 37893442, 2023). "Analysis of UHRF1 RNA and protein expression in human NSCLC cell lines and patient lung adenocarcinoma samples from TCGA demonstrated a tendency towards higher UHRF1 expression in KRAS mutant cell lines." (PMID 37407562, 2023). "In this study, KRAS gene mutation frequency in blood samples was 14.5% in NSCLC cases and 17.0% in lung adenocarcinoma cases." (PMID 37751775, 2023). "KRAS expression was detected in 585 lung adenocarcinoma patients and 550 lung squamous cell carcinoma patients." (PMID 37069494, 2023). "On the other hand, these modules had limited prognostic power in lung adenocarcinomas that were wild type for KRAS." (PMID 36950380, 2023). "In fact, in cancers with frequent KRAS mutations, including PDAC, lung adenocarcinoma (LAUD) and colon adenocarcinoma (COAD), PTRH1 mRNA expression was significantly negatively correlated with KRAS mRNA levels." (PMID 37434177, 2023). "Inhibition of the HSP90 chaperone was evaluated in different lung adenocarcinoma cell lines representing the most relevant molecular alterations (EGFR mutations, KRAS mutations, or EML4-ALK translocation) and wild-type genes found in each tumor subtype." (PMID 37762133, 2023). "EGFR, ALK, BRAF, KRAS, ROS1 are the five common genes in lung adenocarcinoma, and EGFR gene mutation is the most common." (PMID 37340599, 2023). "In this work, we propose a radiogenomic workflow to detect the presence of KRAS and EGFR mutations using radiomic features extracted from computed tomography images of patients affected by lung adenocarcinoma." (PMID 37508774, 2023). "The main oncogenic driver genes found in lung adenocarcinomas are KRAS, EGFR, ALK, BRAF, HER2, PIK3CA, ROS1, and RET." (PMID 37882674, 2023). "The ultimate goal of these studies is to develop better therapies for human patients with KRAS-mutant lung adenocarcinoma." (PMID 37882674, 2023).
lung adenocarcinoma (continued). "Here, the authors show the development of KRAS(G12D)-driven lung adenocarcinoma is dependent on SOS1, with dual roles in both tumor and stroma." (PMID 37730692, 2023). "Using a genetic model to delete Ezh2 in KRAS-driven lung adenocarcinomas, we observed that Ezh2 haplo-insufficient tumors were less lethal and lower grade than Ezh2 fully-insufficient tumors, which were poorly differentiated and metastatic." (PMID 36670102, 2023). "This proteomic assay was used to identify proteins related to HSP90 inhibition responsiveness according to the most relevant molecular alteration in lung adenocarcinoma such as EGFR and KRAS mutations and ALK translocation." (PMID 37762133, 2023). "In order to examine the involvement of HDAC2 in the migration of lung adenocarcinoma cells, we conducted an overexpression of HDAC2 in A549 and H441 cells, both are well used KRAS-mutant lung adenocarcinoma." (PMID 37495623, 2023). "Human lung adenocarcinoma data sets only showed that RANKL expression was significantly higher in KRAS+ lung adenocarcinoma compared to KRAS wildtype lung adenocarcinoma." (PMID 37213294, 2023). "KRAS G12C is the most common KRAS pathogenic variant, occurring in 40–50% of NSCLC cases, and is a critical oncogenic driver found in ~13% of all lung adenocarcinomas." (PMID 37373999, 2023). "The Epidermal Growth Factor Receptor (EGFR) and KRAS, two pivotal components of RTK-ERK signaling pathways, are the most frequent targets for oncogenic driver mutations in lung adenocarcinoma (LUAD)." (PMID 37730692, 2023). "In the third cohort, we determined the KRAS mutation status and the expression levels of CD47, p-STAT3, and miR-34a in 100 pairs of lung adenocarcinoma and normal tissue samples." (PMID 36413402, 2023). "Our model aims to evaluate the status of KRAS mutants in lung adenocarcinoma by combining PET radiomics and machine learning." (PMID 37509345, 2023). "The tumor suppressive function of the chromatin modifier SETD2, at least in the context of KRAS-driven lung adenocarcinoma, is therefore to limit pro-proliferative metabolic pathways by restricting oxidative metabolism and protein synthesis." (PMID 36899051, 2023). "On one hand, silencing of RAF and autophagy inhibition leads to cell cycle arrest and cell death in KRAS mutant cells, a phenotype similar to the one observed in KRAS lung adenocarcinoma when only RAF1 is genetically ablated." (PMID 37020037, 2023). "Another recent study found that KRAS-driven lung adenocarcinoma tumor samples have dramatically increased cell size, but did not examine the effects of KRAS in the absence of additional passenger mutations present in tumor cells." (PMID 38021173, 2023). "Co-mutations in the KRAS proto-oncogene and the LKB1 tumor suppressor gene frequently occur in hyper-metabolic and aggressive human lung adenocarcinoma tumors." (PMID 37190124, 2023). "In this study, we established a positive correlation between KRAS mutation status and CD47 overexpression in patients with lung adenocarcinoma." (PMID 36413402, 2023).
lung adenocarcinoma (continued). "Neutrophils can be subjected to reprogramming as has been observed in an experimental mouse model of KRAS-driven lung adenocarcinoma to favor tumor growth." (PMID 37178819, 2023). "A recent study reported that ILK promotes lung adenocarcinoma progression and metastasis through the regulation of KRAS, the IPP complex and RSU1, with other studies also linking ILK to cancer metastasis." (PMID 37568580, 2023). "Then, we aimed to enhance the understanding of radiomic features associated with KRAS and EGFR mutations in lung adenocarcinoma and to evaluate the effectiveness of the features in accurately classifying mutations." (PMID 37508774, 2023). "It has also been found that regenerating family member (REG4) is highly expressed in KRAS-mutant lung adenocarcinoma, and that silencing REG4 can inhibit cancer cell proliferation and genesis, making it a potential therapeutic target." (PMID 36675641, 2023). "It was found that TRIM58 was positively correlated with an abundance of M2 macrophages and resting mast cells in KRAS-mutant lung adenocarcinoma, and negatively correlated with an abundance of follicular helper T cells." (PMID 36675641, 2023). "Kirsten rat sarcoma viral oncogene homolog (KRAS) and epidermal growth factor receptor (EGFR) are the most frequently mutated oncogenes in human lung adenocarcinoma." (PMID 37985999, 2023). "Firstly, we employed A549 cells as a model for EGFR-TKI-resistant lung adenocarcinoma, which harbors wild-type EGFR and KRAS mutation." (PMID 37886957, 2023). "The aim of this study was to enhance the comprehension of radiomic features linked with KRAS and EGFR mutations in lung adenocarcinoma and evaluate the effectiveness of these features in accurately classifying mutations." (PMID 37508774, 2023). "Here we identify heightened mTORC1-associated gene expression programs and functionally higher levels of oxidative metabolism and protein synthesis as prominent consequences of Setd2 inactivation in KRAS-driven mouse models of lung adenocarcinoma." (PMID 36899051, 2023). "In support of this, ARAF dimers have been found to promote ERK signaling and cell cycle arrest in KRAS-mutated, RAF1-deficient lung adenocarcinoma cell lines." (PMID 37020037, 2023). "Our work uncovers a role for SETD2 in constraining mitochondrial OXPHOS and mTORC1 signaling to limit cellular proliferation in the context of KRAS-driven lung adenocarcinoma." (PMID 36899051, 2023). "Recent studies show the activation of KRAS in colorectal (50%), pancreatic (90%), and lung adenocarcinomas (32%)." (PMID 37511536, 2023). "For example, autophagy was required for the development of KRAS-driven lung adenocarcinomas in mice." (PMID 35725745, 2022). "In KRAS signaling active lung adenocarcinomas, FASN is a primary responder that induces elevated lipogenesis which mediated by the ERK pathway." (PMID 35898882, 2022). "In this study, we identified the number of recurrent genomic aberrations in a lung adenocarcinoma subgroup defined by KRAS LOH status." (PMID 35574381, 2022). "In KRAS-mutant lung adenocarcinoma, the alterations of STK11/LKB1 exert effects in resisting the PD-1/PD-L1 inhibitors." (PMID 36034461, 2022). "By in vivo and in vitro experiments, the effects of the key gene on the biological functions of KRAS mutant lung adenocarcinoma were explored." (PMID 36505791, 2022). "To determine if there is evidence for such a promotional activity in the selection of oncogenic KRAS mutations in humans, we extracted the mutation signatures in the COSMIC database for human KRAS-mutant lung adenocarcinomas." (PMID 35482806, 2022).